RNA5S10 (RNA, 5S ribosomal 10)
Synonyms: RN5S10
Gene: Ribosomal RNA gene on chromosome 1 (228,630,390 to 228,630,508, reverse strand). Ensembl gene ENSG00000199910.
Gene Ontology:
Molecular function: structural constituent of ribosome
Cellular component: ribosome
Homologues: Orthologues: mouse n-R5s117 (100% identical), rat 5S_rRNA (100% identical). Paralogues in human: RNA5S1 (100% identical), RNA5S11 (100% identical), RNA5S12 (100% identical), RNA5S13 (100% identical), RNA5S14 (100% identical), RNA5S15 (100% identical), RNA5S16 (100% identical), RNA5S17 (100% identical), RNA5S2 (100% identical), RNA5S3 (100% identical), RNA5S4 (100% identical), RNA5S5 (100% identical), and 26 more.